JAK2 (Janus kinase 2)
Diseases named in the same sentence as JAK2 in open-access papers (continued):
Sharing a sentence is not in itself a finding about the gene and the disease.
thrombosis (continued). "Taken together, we can conclude that JAK2 V617F mutation is strongly associated with the occurrence of thrombosis in patients with MPN." (PMID 36611455, 2023). "Cases of MPNs with normal CBC were mostly reported in association with splanchnic vein thrombosis, with JAK2 V617F mutation being highly prevalent in this condition, although at low allele burden." (PMID 37841434, 2023). "To date, thrombosis was observed in three cases of young patients with MPN with a positive JAK2 driver mutation." (PMID 36611455, 2023). "In another cohort of Italian patients, the risk of developing thrombosis was 2.5-fold higher in patients with ET (7.1% vs. 2.8%; p = 0.059), and 3.7-fold higher in patients with PV (10.5% vs. 2.8%; p = 0.001) with JAK2 mutations compared with CALR mutation." (PMID 36611455, 2023). "As for venous thrombosis, the cut-off values for JAK2 allele burden are >90.4% and >56.7% for PV and PMF." (PMID 36611455, 2023). "PV is characterised by the presence of a Janus kinase 2 (JAK2) mutation, erythrocytosis, and panmyelosis on bone marrow biopsy and is associated with an increased risk of thrombosis based on age and other risk factors." (PMID 35800822, 2022). "In general, older age (>60 years), the presence of the JAK2 V617F mutation, and a history of thrombosis and/or vascular risk factors are considered high-risk features for thrombotic events in patients with MPNs." (PMID 36561301, 2022). "In particular, patients with ET and CALR mutation are known to have a lower risk of thrombosis compared to those with JAK2 V617F mutation; however, this seems to be different depending on the CALR mutant type." (PMID 36359414, 2022). "In ET, patients with CALR mutations showed male predominance, higher platelet counts, lower hemoglobin levels and leukocyte counts, and a lower risk of thrombosis than patients with JAK2 and MPL mutations." (PMID 36359414, 2022). "Bone marrow proliferation disorders that are associated with Janus Kinase 2 V617F mutation (JAK-2) are known causes of the systemic and cerebral thrombosis—at times despite normal blood counts—for which hematologic treatment exists." (PMID 35493844, 2022). "Further, studies have shown that patients with initial JAK2 mutation demonstrated a higher risk of thrombosis compared to a more indolent course in patients with initial PV-associated TET2 mutation." (PMID 34660059, 2021). "It is important to consider the possibility of increased risk of thrombosis or hemorrhage in PV patients undergoing surgery, in lieu of their underlying JAK2-mutated MPN as well as the generally expected post-surgical risk of thrombosis and bleeding." (PMID 34480106, 2021). "Among patients with variations associated with CHIP (DNMT3A, TET2, ASXL1, JAK2), thrombosis occurred in 5 patients (62%; odds ratio [OR], 5.6; 95% CI, 1.3-15.9) and death in 3 patients (37%; OR, 6.1; 95% CI, 1.3-26.9)." (PMID 34357393, 2021). "Patients aged 60 years and above with either cardiovascular risk factors or JAK2 mutations, as well as any patients presenting with a history of thrombosis, should receive cytoreductive treatment." (PMID 33712866, 2021). "Compared with patients in whom TET2 mutation was acquired first, patients in whom the JAK2 mutation was acquired first had an increased risk of thrombosis and a poor prognosis." (PMID 33653301, 2021). "The association between MPNs with JAK2 rs V617F mutation had been suggested to be linked to splanchnic vein thrombosis." (PMID 33507708, 2021). "By means of this tool, patients are assigned to a low-, intermediate-, or high-risk group based on the criteria of age over 60 years, presence of the driver mutation JAK2-V617F, presence of cardiovascular risk factors, and history of thrombosis." (PMID 33712866, 2021). "At allelic burden greater than 25%, they observed a 7.4-fold increase in the risk of thrombosis as compared to patients with <25% JAK2 V617F allelic burden." (PMID 34833034, 2021).
thrombosis (continued). "Age over 60 years, presence of the driver mutation JAK2-V617F, presence of cardiovascular risk factors, and history of thrombosis were identified to constitute independent risk factors for arterial thrombosis." (PMID 33712866, 2021). "Although MPL-mutated patients share a similar clinical picture with CALR-mutants, the latter group has a lower incidence of thrombosis, especially when compared to JAK2 V617F mutated counterpart (10.5 vs. 25.1%, respectively; p = 0.01)." (PMID 32629973, 2020). "As a matter of fact, also JAK2 V617F mutant allele burden has been related to both arterial (values >25%; p = 0.055) and venous (values > 90%; p = 0.036) thrombosis." (PMID 32629973, 2020). "In this study, JAK2 V617F mutation was associated with low risk for thrombosis in ET patients with odds ratio equal to 0.953 (P=0.9)." (PMID 32292481, 2020). "Age ≥60 years and at least 1 CV risk factor (1 score); thrombosis history and JAK2 mutation (2 scores)." (PMID 32098944, 2020). "In contrast, lower PC (<1000 × 109/L) has been associated with arterial and venous thrombosis (ischemic stroke, deep venous thrombosis, pulmonary embolism, etc.), with an increased risk observed when JAK2 mutation is present." (PMID 32629973, 2020). "Patients with the JAK2 mutation had a higher prevalence of a history of thrombosis and age older than 65 years." (PMID 32158346, 2020). "In this study, JAK2 mutation was associated with older age, high-risk disease and increased incidence of thrombosis or haemorrhage compared to CALR positive and triple-negative ET and PMF." (PMID 32164591, 2020). "Only for ET, the IPSET-thrombosis system that includes age, previous thrombosis, cardiovascular risk factors, and JAK2-V617F mutation is the recommended prognostic system and it should be scored in all patients at diagnosis." (PMID 32280344, 2020). "Risk factors associated with thrombosis included age (P = .027), previous thrombosis (P = .041), leukocytosis (P = .047), and JAK2 V617F allele burden (P = .014)." (PMID 30848334, 2019). "A high JAK2 V617F allele burden (> 75%) was associated with a 3.56-fold higher relative risk (95% CI, 1.47–7.1; P = .004) of total thrombosis compared with a reference population." (PMID 30848334, 2019). "JAK2 inhibitor attenuated collagen-induced platelet aggregation in a dose-dependent manner, so an association between thrombosis and JAK2 via effect on platelet seems counterintuitive." (PMID 30508136, 2019). "These JAK2 V617F first cells appear to favour a polycythaemia phenotype, with an increased risk of thrombosis in the patient group whilst the transcriptional profile of the cells was significantly altered dependent on the first acquired mutation." (PMID 30558676, 2018). "Among the risk factors, previous thrombosis, old age (≥ 60 years) and hypertension were significantly correlated to positive JAK2 V617F mutation." (PMID 30564475, 2018). "Summing up, in MPNs significant predictors of a first VTE are the previous history of VTE, older age, and inherited thrombophilia, similarly to the general population; moreover, the carriers of the JAK2 V617F mutation are more prone to venous thrombosis." (PMID 29946112, 2018). "The history of thrombosis, age ≥ 60 years and hypertension are risk factors that can be correlated to JAK2 V617F mutation." (PMID 30564475, 2018). "There were more arterial thrombosis events seen in those with JAK2 V617F mutation as compared to venous thrombosis events (23.1% vs 4.4%)." (PMID 30564475, 2018). "The previous history of thrombosis, advanced age ≥ 60 years and hypertension are strong risk factors correlated with JAK2 V617F detection in our population." (PMID 30564475, 2018). "In ET the presence of both JAK2 V617F and inherited thrombophilia has been reported to produce an additive risk of thrombosis in younger patients." (PMID 29946112, 2018).
thrombosis (continued). "In our ET patients, median age at diagnosis, the incidence of thrombosis and bleeding at diagnosis, and JAK2 mutation positivity were compatible with literature findings." (PMID 27094252, 2017). "In our study, the incidence of JAK2 mutation, the history of thrombosis, and the median age at diagnosis were lower than in the literature." (PMID 27094252, 2017). "After univariate analysis, older age, higher leukocyte count at diagnosis, and JAK2 positivity were risk factors for thrombosis." (PMID 27094255, 2016). "Older age, higher leukocyte count at diagnosis, and JAK2 mutation positivity were risk factors for thrombosis after univariate analysis." (PMID 27094255, 2016). "Older age, higher leukocyte count at diagnosis, and JAK2 mutation positivity were risk factors for thrombosis." (PMID 27094255, 2016). "As regards to the localization of venous thrombosis among ET patients, 20% of the ET patients with high JAK2V617F allele burden experienced deep vein thrombosis (DVT) whereas the frequency of DVT was 2.3% in patients with wild-type JAK2." (PMID 25584101, 2015). "Traditional factors that increase vascular risk in the MPN include age over 60 and prior thrombosis, and newly suggested risk factors include leukocytosis and increased JAK2 V617F allele burden." (PMID 22084670, 2011). "All patients had homozygous JAK2 mutation, which is associated in recent studies with increased risk of portal, mesenteric thrombosis." (PMID 21505581, 2011). "The JAK2 gene mutation is associated with an increased risk of thrombosis." (PMID 40572650, 2025). "JAK2 V617F mutation is associated with significantly iIncreased risk of thrombosis." (PMID 40926892, 2025). "Additionally, the presence of the JAK2 mutation contributes to the patient's phenotype with venous thrombosis and MPN." (PMID 40177144, 2025). "Additionally, higher absolute neutrophil counts and the JAK2 V617F allele burden are linked to an increased risk of venous thrombosis." (PMID 40507313, 2025). "The JAK2 V617F mutation is present in approximately half of ET cases, and recent reports suggest that patients harboring this mutation experience a higher incidence of venous thrombosis." (PMID 40809165, 2025). "Notably, individuals with JAK2 V617F CH and higher VAFs exhibited elevated blood cell counts and had a greater susceptibility to venous thrombosis, PE, or cerebrovascular events." (PMID 38338802, 2024). "Patients with the JAK2 mutation often present with varied clinical features, such as erythrocytosis, leukocytosis, or thrombocytosis, and have an increased risk of complications like thrombosis and disease progression." (PMID 39877786, 2024). "Interestingly, a remarkably less frequent (p = 0.03) venous thrombosis was observed in patients with ET with CALR mutation than those with JAK2 mutation." (PMID 36611455, 2023). "However, an India cohort study indicated that the JAK2 V617F mutation was found at a very low frequency and displayed a weak association with thrombosis, particularly for venous thrombosis present in sites other than the splanchnic region." (PMID 36611455, 2023). "JAK2-V617F, the most prevalent mutation in MPNs, has been shown to activate a number of integrins on mature myeloid cells, including granulocytes and erythrocytes, which increase adhesion and drive venous thrombosis in murine knock-in/out models." (PMID 35328626, 2022). "Additionally, in our cohort, only 1 true venous infarction case was documented (in patient with APLA), and only 2 cases of confirmed recurrent thrombosis were seen (1 in the JAK-2 positive patient and 1 associated with idiopathic thrombosis)." (PMID 35493844, 2022). "Additionally, we showed that the JAK-2-mutation-associated thrombosis was associated with a poorer clinical course in 3 otherwise healthy patients (a non-significant trend, probably due to overall low incidence)." (PMID 35493844, 2022). "In conclusion, the JAK-2 mutation is still underdiagnosed in the cases of idiopathic thrombosis." (PMID 35493844, 2022).
thrombosis (continued). "In our study, the positivity rate for JAK-2 mutation reached 13%, which is less than previously reported in other cases of systemic venous thrombosis but higher than expected, especially in the cases of first-ever thrombosis with normal blood counts." (PMID 35493844, 2022). "Interestingly, in PMF, a recent meta-analysis found that CALR-mutated patients displayed a lower risk of splenomegaly (OR 0.47, 95% CI 0.29–0.78) and thrombosis (OR 0.52, 95% CI 0.29–0.92) when compared with JAK2-mutated patients." (PMID 35328626, 2022). "The presence of the JAK2 V617F mutation, a positive history for thrombosis or the employment of cytoreduction versus antiplatelet therapy did not impact on CECs levels in ET, nor were CECs levels associated with age, sex, ET duration or complete blood count parameters." (PMID 34357048, 2021). "Patients with positive JAK2 V617F mutation were associated with higher odds in presence of previous thrombosis (OR = 2.624, 95% CI 1.717, 4.009), old age (> 60 years) (OR = 1.691, 95% CI 1.215, 2.354) and presence of hypertension (OR = 1.688, 95% CI 1.234, 2.310)." (PMID 30564475, 2018). "This thrombosis risk appears to be mediated in part by viscosity from increased haematocrit, in part by increased binding to endothelial laminin as a result of an JAK2 V617F driven activation of Lu/BCAM and from increased neutrophil extracellular trap formation." (PMID 30558676, 2018). "Based on our results and knowledge of the literature, JAK2 mutation positivity could be another high-risk factor for thrombosis along with age, previous thrombosis, and leukocytosis." (PMID 27094255, 2016). "Furthermore; patients with JAK2 V617F mutation have demonstrated recurrent episodes of venous thrombosis." (PMID 23876158, 2013). "Recurrent episodes of venous thrombosis have been closely correlated with JAK2 V617F mutation." (PMID 23876158, 2013). "There are many factors that contribute to the development of thrombosis, including congenital (hereditary thrombophilia) and acquired factors (such as antiphospholipid syndrome, inflammation, atherosclerosis, the JAK2 mutation, and MPN-associated thrombosis), that may be frequently observed." (PMID 40572650, 2025). "In HSCs with JAK2 mutations, there is an overproduction of activated leukocytes and platelets, leading to the release of excessive reactive oxygen species, pro-inflammatory cytokines, and thromboxane, all of which collectively increase the risk of arterial and venous thrombosis." (PMID 39395952, 2024). "Age, leukocytosis, cardiovascular risk factors, JAK2 V617F mutation and other high-risk mutations were identified as significant predictors of arterial thrombosis in these patients; the only predictor of venous thrombosis was a history of thrombosis, particularly venous thrombosis." (PMID 39114304, 2024). "Thus, further exploration is required to clarify whether the JAK2 germline variation is a risk factor of thrombosis." (PMID 22251709, 2012). "We measured the levels of D-dimers as a marker of thrombosis and found them significantly increased in the young Jak2-R1063H group." (PMID 40841769, 2025). "In JAK2-mutant CHIP, treatment with the JAK2 inhibitor ruxolitinib reduced the formation of abnormal neutrophil extracellular traps and deep vein thrombosis as well as the levels of IL-18 in the circulation." (PMID 40076674, 2025). "Incidence rates of major arterial/venous thrombosis for JAK2, type 1/type 1-like CALR, type 2/type 2-like CALR, MPL-mutated and TN cases were 14%/8%, 11%/6%, 12%/9%, 13%/0%, and 6%/2%, respectively." (PMID 38238303, 2024). "Thrombotic MPN patients carried almost exclusively JAK2 V617F mutation (90.6% of cases), this finding being consistent with the previously established etiological role of this mutation in MPN‐associated thrombosis." (PMID 39183370, 2024).
thrombosis (continued). "Incidence rates of major arterial/venous thrombosis for JAK2, type 1/type 1-like CALR, type 2/type 2-like CALR, MPL-mutated and TN cases were 16%/13%, 7%/5%, 7%/2%, 13%/7%, and 18%/12%, respectively." (PMID 38238303, 2024). "Of note, the incidence of both arterial and venous thrombosis was lower in CALR mutated and TN patients, compared to JAK2 and MPL mutated." (PMID 38238287, 2024). "There are four risk categories for thrombosis in MPN patients: age, thrombosis history, and JAK-2 mutation." (PMID 38606222, 2024). "Jalowiec reported that 17 % patients with JAK2 unmutated polycythaemia patients suffered a thrombosis in a 10-year period, with half of the events occurring in the arterial and the other half in the venous system." (PMID 39309680, 2024). "Quantitative and qualitative alterations of platelet, erythrocytes, leukocytes and endothelial cells, caused by gain-of-function mutations in JAK2, CALR or MPL, are implicated in the pathogenesis of thrombosis in MPN." (PMID 36768584, 2023). "The combination of JAK2-V617F and lower IPSS was independently associated with thrombosis in the multivariate model when adjusted for previous thrombosis, hemoglobin levels and cytoreductive therapy." (PMID 37958701, 2023). "As for other types of thrombosis, JAK2 V617F can present in patients with cerebral venous thrombosis irrespective of blood count (p < 0.0001) and as one of the early symptoms of MPN." (PMID 36611455, 2023). "In this prospective study of 585 PMF patients, factors that significantly distinguished patients experiencing thrombosis post-diagnosis of PMF in the univariate model were younger age, lower IPSS and JAK2-V617F mutation." (PMID 37958701, 2023). "In the cases of PV- or ET-related thrombosis, antiplatelet treatment is usually sufficient, combined with specific hematological treatment such as hydroxyurea or JAK-2-specific inhibitors." (PMID 35493844, 2022). "This indicates an important role of granulocytes in JAK2-V617F-induced pathological deep vein thrombosis." (PMID 35328626, 2022). "In a recent study, RNA sequencing in granulocytes of PV patients documented higher expression levels of F3, SELP, VEGFA, and SLC2A1, that were directly correlated with JAK2 expression and JAK2V617F allele burden in patients with a history of thrombosis." (PMID 34897288, 2021). "Despite the risk factors for vascular events are only partially defined, major determinants include JAK2 status, age, neutrophil count, and a positive history of thrombosis." (PMID 34830822, 2021). "Our findings are in line with the observations of Sozer and Rosti, while differ from Teofili’s study, in which the JAK2 positive ECFCs were described only in a subset of patients with thrombosis." (PMID 34685741, 2021). "This is in agreement with other studies which found that the incidence of thrombosis was 14.5% in JAK2 positive and 5% in CALR positive patients." (PMID 32292481, 2020). "We have developed a cost-effectiveness model that uses the JAK2 burden as a surrogate endpoint to predict time to DP (AL, MF, and thrombosis) and death in PV." (PMID 32685599, 2020). "Then again, we performed multivariable Cox regression analyses, examining age, sex, white blood cell count, hemoglobin, platelet count, lactate dehydrogenase, mutational status of JAK2/CALR, splenomegaly, and thrombosis." (PMID 27486987, 2016). "The JAK2+/CALR- group had higher white blood cell counts and levels of hemoglobin and lactate dehydrogenase and higher rates of splenomegaly and thrombosis than did the JAK2-/CALR-group." (PMID 27486987, 2016). "Our patient was classified as having intermediate thrombotic risk (age > 60 years, JAK2-negative, no history of thrombosis)." (PMID 40422594, 2025). "Despite the considerable portion of patients with splanchnic venous thrombosis, a small subset of those CVTs can be identified as carriers of the JAK2 V617F mutation, even when they do not display evident signs of MPNs." (PMID 38338802, 2024).